PGM2 (phosphoglucomutase 2)
Description:
Catalyzes the conversion of the nucleoside breakdown products ribose-1-phosphate and deoxyribose-1-phosphate to the corresponding 5-phosphopentoses. Catalyzes the reversible isomerization of alpha-D-glucose 1-phosphate to alpha-D-glucose 6-phosphate but with a lower catalytic efficiency. The mechanism proceeds via the intermediate compound alpha-D-glucose 1,6-bisphosphate. In vitro, also has a low glucose 1,6-bisphosphate synthase activity which is most probably not physiologically relevant.
Synonyms: MSTP006; FLJ10983
Tractability: Antibody: its Gene Ontology location is reachable by antibodies, with high confidence. PROTAC: ubiquitination databases record sites on it; its protein half-life has been measured.
Target class: Isomerase; Enzyme
Gene: Protein-coding gene on chromosome 4 (37,826,660 to 37,863,028, forward strand). Ensembl gene ENSG00000169299.
Subcellular location: Cytoplasm, cytosol
Subcellular location (Human Protein Atlas): Intermediate filaments; Cytosol
Pathways (Reactome):
Immune System: Neutrophil degranulation
Metabolism: Pentose phosphate pathway
Gene Ontology:
Molecular function: phosphoglucomutase activity; phosphopentomutase activity; protein binding; intramolecular phosphotransferase activity; magnesium ion binding
Biological process: purine ribonucleoside salvage; carbohydrate metabolic process; glycogen biosynthetic process; glycogen catabolic process
Cellular component: cytosol; extracellular exosome; extracellular region; ficolin-1-rich granule lumen; secretory granule lumen
Genetic constraint (gnomAD): Loss-of-function variants: 21 observed, 25.81 expected, observed/expected ratio (o/e) 0.81, 90% interval 0.58 to 1.17. The upper end of that interval is the gene's LOEUF score, 1.17, which puts it in group 5 of 6, group 1 being the genes least tolerant of losing a copy. Missense variants: 282 observed, 325.03 expected, observed/expected ratio (o/e) 0.87, 90% interval 0.79 to 0.96. Synonymous variants: 122 observed, 117.5 expected, observed/expected ratio (o/e) 1.04, 90% interval 0.9 to 1.21.
Homologues: Orthologues: chimpanzee PGM2 (99% identical), macaque PGM2 (98% identical), dog PGM2 (93% identical), mouse Pgm2 (92% identical), rabbit PGM2 (92% identical), guinea pig PGM2 (92% identical), rat Pgm2 (91% identical), pig PGM2 (87% identical), tropical clawed frog pgm2 (77% identical), zebrafish pgm2 (73% identical), Caenorhabditis elegans pgm-1 (18% identical), Drosophila melanogaster Pgm1 (18% identical). Paralogues in human: PGM2L1 (59% identical), PGM1 (20% identical), PGM5 (18% identical), PGM3 (17% identical), PRTFDC1 (9% identical), HPRT1 (8% identical).
Diseases named in the same sentence as PGM2 in open-access papers:
PGM2 is named in the same sentence as 11 diseases in open-access papers, as found by Europe PMC text mining. Sharing a sentence is not in itself a finding about the gene and the disease. The quoted sentences say what the papers report.
colorectal cancer (2 papers, 2020 to 2023). A primary or metastatic malignant neoplasm that affects the colon or rectum. "Interestingly, the gene PGM2 has not been shown to be a biomarker for colorectal cancer while the gene ASRGL1 has been shown to be prognostic in the prediction of endometrial cancer." (PMID 37286944, 2023).
melanoma (2 papers, 2023 to 2024). A malignant, usually aggressive tumor composed of atypical, neoplastic melanocytes. "Several cytosolic (PGM2, LDHA and pPKM2) and mitochondrial (UQCRC1, COX4 and ATP5B) enzymes are downregulated by HPF treatment, suggesting a generalized reduction of vital functions in melanoma cells." (PMID 36674794, 2023).
colon cancer (1 paper, 2021). "qRT-PCR was performed from RNA extracted from 43 pairs of colon cancer and adjacent normal tissues to observe the relative expression levels of eight GRGs (P4HA1, STC2, CHPF2, PMM2, PGM2, ENO3, PPARGC1A, and PPP2CB)." (PMID 34422808, 2021).
tumor (4 papers, 2020 to 2024). "LDHA, PGM2 and the phosphorylated form of pyruvate kinase M2, the level of which is high in tumor cells, are all less expressed." (PMID 36674794, 2023). "Although PGM2 and RHNO1 have not been reported in CRC, they are involved in other tumor developments." (PMID 33537062, 2020).
cancer (1 paper, 2025). A tumor composed of atypical neoplastic, often pleomorphic cells that invade other tissues. "Considering these findings, targeting PGM2 could effectively inhibit uridine metabolism and be utilized as a target in treating cancer." (PMID 40804482, 2025).
infection (1 paper, 2022). The state of being infected such as from the introduction of a foreign agent such as serum, vaccine, antigenic substance or organism. "Interestingly, unlike ldh1/ldh2 and eno1/eno2 which are expressed in a stage-dependent manner, both PGM isoforms (pgm1 and pgm2) were upregulated 6.4 and 3.1 folds, respectively, in the chronic stage, 28 days post-infection (dpi)." (PMID 35597992, 2022).
metabolic disease (1 paper, 2021). A congenital disorder (due to inherited enzyme abnormality) or acquired (due to failure of a metabolically important organ) disorder resulting from an abnormal metabolic process. "PGM2 has been associated with metabolic disease in GWAS studies." (PMID 33755012, 2021).
PGM2 also shares sentences with these, for which no sentence is quoted: endometrial cancer (1 paper); glioblastoma (1); ovarian carcinoma (1); pancreatic cancer (1).